LINC00596 (long independently transcribed non-coding RNA 596)
Synonyms: CNSLT1I7G; formerly C14orf165
Gene: Long non-coding RNA gene on chromosome 14 (23,922,247 to 23,934,568, reverse strand). Ensembl gene ENSG00000259334.
Subcellular location: Membrane